ASF1B (anti-silencing function 1B histone chaperone)
Description:
Histone chaperone that facilitates histone deposition and histone exchange and removal during nucleosome assembly and disassembly. Cooperates with chromatin assembly factor 1 (CAF-1) to promote replication-dependent chromatin assembly. Also involved in the nuclear import of the histone H3-H4 dimer together with importin-4 (IPO4): specifically recognizes and binds newly synthesized histones with the monomethylation of H3 'Lys-9' (H3K9me1) and diacetylation at 'Lys-5' and 'Lys-12' of H4 (H4K5K12ac) marks in the cytosol. Does not participate in replication-independent nucleosome deposition which is mediated by ASF1A and HIRA. Required for gonad development.
Synonyms: CIA-II; FLJ10604
Tractability: PROTAC: ubiquitination databases record sites on it.
Gene: Protein-coding gene on chromosome 19 (14,119,512 to 14,136,622, reverse strand). Ensembl gene ENSG00000105011.
Subcellular location: Nucleus; Cytoplasm, cytosol
Subcellular location (Human Protein Atlas): Nucleoplasm
Gene Ontology:
Molecular function: histone chaperone activity; protein binding; histone binding
Biological process: DNA replication-dependent chromatin assembly; transcription elongation-coupled chromatin remodeling; protein import into nucleus; chromatin organization; nucleosome assembly
Cellular component: chromatin; nucleoplasm; nucleus; protein-containing complex; histone acetyltransferase complex; cytosol
Genetic constraint (gnomAD): Loss-of-function variants: 10 observed, 18.64 expected, observed/expected ratio (o/e) 0.54, 90% interval 0.33 to 0.91. The upper end of that interval is the gene's LOEUF score, 0.91, which puts it in group 3 of 6, group 1 being the genes least tolerant of losing a copy. Missense variants: 239 observed, 279.04 expected, observed/expected ratio (o/e) 0.86, 90% interval 0.77 to 0.95. Synonymous variants: 100 observed, 112.3 expected, observed/expected ratio (o/e) 0.89, 90% interval 0.76 to 1.05.
Homologues: Orthologues: chimpanzee ASF1B (100% identical), macaque ASF1B (99% identical), pig ASF1B (96% identical), dog ASF1B (95% identical), rat Asf1b (93% identical), mouse Asf1b (92% identical), guinea pig ASF1B (90% identical), tropical clawed frog asf1b (75% identical), zebrafish asf1bb (75% identical), zebrafish asf1ba (74% identical), dog ASF1B (67% identical), Drosophila melanogaster asf1 (60% identical), and 2 more. Paralogues in human: ASF1A (71% identical).
Diseases named in the same sentence as ASF1B in open-access papers:
ASF1B is named in the same sentence as 75 diseases in open-access papers, as found by Europe PMC text mining. Sharing a sentence is not in itself a finding about the gene and the disease. The quoted sentences say what the papers report.
breast carcinoma (17 papers, 2015 to 2025). "In conclusion, ASF1B is significantly upregulated in breast cancer and is associated with poor clinical outcomes and distinct immune signatures." (PMID 40944429, 2025). "This study aims to define the expression pattern of ASF1B in breast cancer, assess its prognostic significance, explore its association with immune infiltration, and lay the groundwork for future translational research." (PMID 40944429, 2025). "In this study, we conducted a comprehensive bioinformatics and clinical validation analysis to investigate the expression pattern, clinical relevance, and immunological associations of anti‐silencing function protein 1B (ASF1B) in breast cancer." (PMID 40944429, 2025). "Clinical data further showed that high ASF1B expression was significantly associated with HER2‐positive breast cancer (p = 0.026)." (PMID 40944429, 2025). "Recently, an increasing number of studies have indicated that the dysregulated expression of ASF1B is associated with many cancer types, such as breast cancer, prostate cancer, cervical cancer, and clear cell renal cell carcinoma." (PMID 35087760, 2021). "ASF1A influence cell recovery from DNA damage while ASF1B is associated with defective cell growth, sensitivity during replication stress and breast cancer metastasis." (PMID 32257110, 2020). "Given the central role of ASF1B in chromatin dynamics and proliferation, we hypothesized that ASF1B expression may be elevated in breast cancer tissues and associated with adverse clinicopathologic features and prognosis." (PMID 40944429, 2025). "In addition, high expression of ASF1b expression was associated with increased incidence of breast cancer in progression and metastasis." (PMID 35399734, 2022). "The higher expression of ASF1B may alter nucleosome assembly, resulting in genome instability and the promotion of tumorigenesis, and has been demonstrated to have an association with increased metastasis and poor survival of breast cancer." (PMID 26655252, 2016). "ASF1B is highly expressed in breast cancer and correlates with poor prognosis and immune cell infiltration." (PMID 40944429, 2025). "Despite these limitations, our study is, to our knowledge, the first to integrate large‐scale database analysis with clinical sample validation to characterize ASF1B in breast cancer, especially its link to HER2 biology and immune infiltration." (PMID 40944429, 2025). "TIMER database analysis revealed that ASF1B expression positively correlated with infiltration of B cells, neutrophils, and dendritic cells and negatively with macrophages (all p < 0.05) in breast cancer tissues." (PMID 40944429, 2025). "Specifically, ASF1B levels were significantly higher in breast cancer tissues compared to normal controls, as confirmed by the GEPIA2 database (p < 0.05)." (PMID 40944429, 2025). "ASF1B expression was significantly elevated in breast cancer tissues compared to normal tissues (p < 0.05)." (PMID 40944429, 2025). "Our findings demonstrate that ASF1B is significantly overexpressed in breast cancer tissues compared to normal controls, and that its elevated expression is associated with poor prognosis, aggressive molecular features, and altered immune cell infiltration." (PMID 40944429, 2025). "Previous studies suggest that abnormal ASF1B expression contributes to the occurrence and progression of different cancers, including cervical cancer (CC), thyroid cancer (TC), breast cancer (BC), prostatic cancer (PCa) and lung cancer (LC)." (PMID 36114946, 2023). "ASF1b has been shown as an oncogene to promote cervical cancer, breast cancer, cell renal cell carcinoma and prostate cancer 23, 30-32." (PMID 35399734, 2022). "It has been suggested that ASF1B overexpression promotes tumor progression and metastasis in several cancers, such as breast cancer, cervical cancer, clear cell renal cell carcinoma, and prostate cancer." (PMID 35174076, 2022).
breast carcinoma (continued). "It has also been reported that high ASF1B expression is closely related to poor outcomes of patients with renal cell cancer, cervical cancer, and breast cancer." (PMID 35360875, 2022). "Increased ASF1B expression levels have been linked to the prognosis of LUAD and breast cancer patients." (PMID 34568067, 2021). "Previous studies evaluating the effect of ASF1B on cancer have shown that ASF1B, as an oncogenic gene, promotes tumor growth in breast cancer, cell renal cell carcinoma, cervical cancer, prostate cancer and lung cancer." (PMID 35087760, 2021). "Prior work suggests that ASF1B is a key regulator of proliferation, apoptosis, and the cell cycle in prostate cancer, cervical cancer, clear cell renal cell carcinoma, and breast cancer." (PMID 34568067, 2021). "ASF1B level is significantly enhanced in tumor samples and metastatic breast cancer cell lines significantly increase the likelihood of developing breast cancer metastasis." (PMID 32257110, 2020). "Previous studies evaluating the effect of ASF1B on cancers revealed that ASF1B functions as an oncogene to promote tumor growth in breast cancers, cell renal cell carcinoma, prostate cancers." (PMID 32848135, 2020). "Kaplan–Meier analysis showed that breast cancer patients with high ASF1B expression had significantly reduced 10‐year overall survival (OS; HR = 1.42, p < 0.001) and recurrence‐free survival (RFS; HR = 1.24, p < 0.001), indicating that elevated ASF1B is associated with a worse prognosis." (PMID 40944429, 2025). "ASF1B expression in breast cancer was analyzed using the GEPIA2 and BEST databases." (PMID 40944429, 2025). "Similarly, the oncogenic role of ASF1B has been reported in multiple cancers, such as breast cancer, clear renal cell carcinoma and prostate cancer." (PMID 36114946, 2023). "In addition, ASF1B was also a prognostic marker for breast cancer as well as lung adenocarcinoma, and occupied an important position in the initiation and progression of tumours." (PMID 36947060, 2023). "ASF1B protein is increased by approximately 5.5-fold in tumor versus normal cells, and it is significantly correlated with the p60, p150, and Ki67 proliferation markers in breast cancer." (PMID 35360875, 2022). "ASF1B has been identified early in the disease progression of breast cancer." (PMID 35280822, 2022). "It supported previous studies that ASF1B expression was elevated in cervical and breast cancers." (PMID 34490109, 2021). "The expression of the chromatin regulator histone chaperone anti-silencing function 1b (ASF1b) protein is upregulated in breast cancer, correlates significantly with Κi-67 expression, and is an independent prognostic factor of disease progression and metastasis." (PMID 34073937, 2021). "ASF1B has been shown to promote breast cancer, prostate cancer, cell renal cell carcinoma." (PMID 32848135, 2020). "In addition, it has been reported that ASF1B is necessary for breast cancer cell proliferation, indicating its prediction for the outcome of breast cancer patients." (PMID 26336826, 2015). "Thus, the expression of ASF1B has high prognostic value in breast cancer." (PMID 35360875, 2022). "Of particular interest is the significant correlation between high ASF1B expression and HER2‐positive breast cancer." (PMID 40944429, 2025). "For example, ASF1B is the ASF1 isoform necessary for cell proliferation in breast cancer, while ASF1A is not required in this process." (PMID 26336826, 2015). "It has been reported that ASF1B, rather than ASF1A, is critical for proliferation and has highly significant prognostic value in breast cancer and cervical cancer." (PMID 35360875, 2022).
cervical cancer (16 papers, 2018 to 2025). A primary or metastatic malignant neoplasm involving the cervix. "Taken together, these results suggest that impaired expression of ASF1B inhibits cervical cancer growth and induces apoptosis, which is associated with modulation by the ASF1B/CDK9 pathways." (PMID 32848135, 2020). "ASF1B has been reported to be implicated in various cellular functions related to cancer pathogenesis and progression, such as cervical cancer, prostate cancer, and clear cell renal cell carcinoma, which could enhance cell growth and migration, but reduce cell apoptosis." (PMID 34872448, 2021). "Our data implied that ASF1B was closely associated with proliferation, migration, and anti-apoptosis in cervical cancer cells and might be considered a novel therapeutic target and prognostic indicator in cervical cancer patients." (PMID 32848135, 2020). "Prior studies in gastric, lung, and cervical cancers have suggested that ASF1B modulates cell cycle regulators such as Cyclin E1, CDK2, and MYC, consistent with our enrichment results showing associations with DNA replication and mitotic pathways." (PMID 40944429, 2025). "Through this search, we found that overexpression of the positively correlated gene, ASF1B, accelerated the proliferation of cervical cancer cells." (PMID 39555702, 2024). "In cervical cancer, ASF1B promotes cell invasion and affects prognosis by activating the Wnt/β-Catenin signaling pathway." (PMID 35280822, 2022). "Several studies indicate that ASF1B plays an important role in various cancers, namely, prostate cancer, cervical cancer, and liver cancer." (PMID 35875094, 2022). "According to a recent study, ASF1B can promote cervical cancer development by stabilizing CDK9, whereas inhibiting ASF1B can stop cervical cancer from growing by interrupting the cell cycle." (PMID 35875094, 2022). "ASF1B Is a histone chaperone which facilitates histone deposition, exchange, and removal during nucleosome assembly/disassembly; in cervical cancer it was observed that it functions as an oncogene accelerating cancer cells proliferation." (PMID 33649335, 2021). "Recent findings have greatly expanded our understanding of the role of ASF1B in the pathogenesis of various cancers, including prostate cancer, clear cell renal cell carcinoma, and cervical cancer." (PMID 34872448, 2021). "We detected that knockdown of ASF1B significantly suppressed cervical cancer cell proliferation and clonogenic survival." (PMID 32848135, 2020). "We demonstrated that disruption of ASF1B not only suppressed cervical cancer cell growth in vitro but also slowed cervical cancer cell-derived tumor growth in vivo." (PMID 32848135, 2020). "We also found that ASF1B knockdown effectively inhibited cervical cancer cell migration by wound healing and transwell assays." (PMID 32848135, 2020). "The study of xenograft tumors in vivo with AAV-shRNA-ASF1B administration further supported that ASF1B silencing leads to the inhibition of tumor growth in cervical cancer cells." (PMID 32848135, 2020). "Compared with the scrambled cervical cancer cells, ASF1B-shRNA-transfected cervical cancer cells showed significantly decreased invasiveness (p < 0.01)." (PMID 32848135, 2020). "Positive staining for ASF1B was stronger in cervical cancer tissues than in adjacent tissues (p < 0.05)." (PMID 32848135, 2020). "Silence of ASF1B suppressed cervical cancer cell growth in vitro and in vivo, while, ASF1B overexpression accelerated cancer cell proliferation." (PMID 32848135, 2020). "ASF1B downregulation inhibited cell growth and migration in cervical cancer cells in vitro, which encouraged us to investigate the effects of ASF1B on tumor growth in vivo." (PMID 32848135, 2020). "Our study focuses for the first time on the oncogenic activity of ASF1B required to develop cervical cancer tumorigenesis." (PMID 32848135, 2020).
cervical cancer (continued). "Here, we induced ASF1B knockdown and overexpression in cervical cancer cell lines and detected the biological behavior changes in vitro." (PMID 32848135, 2020). "A colony formation assay was also used to investigate the effect of ASF1B on cervical cancer cell growth." (PMID 32848135, 2020). "Conversely, ectopic expression of ASF1B accelerated cancer cell migration (p < 0.01) and increased invasiveness in cervical cancer cells (p < 0.01)." (PMID 32848135, 2020). "Subsequently, we induced ASF1B silencing and overexpression to investigate its function in cervical cancer progression." (PMID 32848135, 2020). "This confirmed that ASF1B plays a role as an oncogene in cervical cancer cells." (PMID 38164276, 2024). "Extensive studies have reported that ASF1B is significantly upregulated in tumor tissues and promotes progression of various cancers, including prostate cancer, cervical cancer, and clear cell renal cell carcinoma, but there has been no previous report of its role in HCC." (PMID 34336642, 2021). "Importantly, in vivo studies indicate that knockdown of ASF1B in cervical cancer cells obviously slowed tumor growth in the recipient mice." (PMID 32848135, 2020). "All these data illustrated the differential expression of ASF1B in distinct cervical cancer cells." (PMID 32848135, 2020). "Wound healing assays were performed to test whether the ASF1B gene impacts cervical cancer cell motility." (PMID 32848135, 2020). "Next, we examined whether ASF1B was overexpressed in different cervical cancer cell lines: CaSki and HeLa cells." (PMID 32848135, 2020). "We showed that ASF1B functions as an oncogene in cervical cancer cells." (PMID 32848135, 2020). "To further elucidate the underlying mechanism of ASF1B and CDK9 in cervical cancer progression, we hypothesized that ASF1B knockdown reduces CDK9 protein levels by promoting its degradation." (PMID 32848135, 2020). "Taken together, tumorigenic ASF1B could be targeted to suppress cervical cancer tumor growth by inducing apoptotic cell death." (PMID 32848135, 2020). "However, very little was found in the literature describing ASF1B as a pivotal oncogenic gene modulating cervical cancer growth." (PMID 32848135, 2020). "These works indicated that ASF1B might promote cervical cancer progression." (PMID 32848135, 2020). "Subsequently, we further confirmed that ASF1B and CDK9 are the factors of a nuclear complex to promote cervical cancer progression by co-IP and colocalization of ASF1B and CDK9 in the nucleus." (PMID 32848135, 2020). "However, the expression and function of ASF1B in cervical cancer remain unclear." (PMID 32848135, 2020). "According to the literature, ASF1B interacts with CDK9 in cervical cancer cells, but it has not been reported in liver cancer cells." (PMID 35087760, 2021).
prostate carcinoma (12 papers, 2020 to 2024). A carcinoma that arises from epithelial cells of the prostate gland. "In prostate cancer, ASF1B promotes cancer progression by affecting the PI3K/AKT signaling pathway." (PMID 35280822, 2022). "Moreover, ASF1b levels also identify the aggressivity of prostate cancer subtypes, with high tumor N stage and M stage 31." (PMID 35399734, 2022). "A previous study demonstrated that high ASF1B expression is highly correlated with prostate cancer (PCa) lymph node metastasis (TNM) staging and that silencing ASF1B inhibits the PI3K/Akt signaling pathway, thereby suppressing PCa cell proliferation and promoting apoptosis and cell cycle arrest." (PMID 34472711, 2021).